THY1 (Thy-1 cell surface antigen)
Diseases named in the same sentence as THY1 in open-access papers (continued):
Sharing a sentence is not in itself a finding about the gene and the disease.
nephritis (32 papers, 2010 to 2025). Inflammation of renal tissue. "We established anti‐Thy‐1 nephritis and co‐culture system to explore the underlying mechanism of ECs proliferation in vivo and in vitro." (PMID 33987885, 2021). "It is worth mentioning that everolimus treatment until the end of the proliferative phase of anti-Thy1-induced nephritis (approximately 2 weeks) caused marked destruction of the glomerular architecture leading to a 60% mortality rate." (PMID 35008770, 2021). "The anti-Thy1 nephritis rat model exhibited severe glomerular hypertrophy, MCs hyperplasia, and mesangial matrix deposition, accompanied by focal capillary loop compression and nodular lesions." (PMID 41345104, 2025). "Using transcriptome data from the anti-Thy1 nephritis rat model, we finally identified 14 DEGs, among which NR4A1 was significantly downregulated in renal tissues of IgAN." (PMID 41345104, 2025). "Here, we determined that CX3CL1 expression in mesangial cells and CX3CR1+ monocyte/macrophage infiltration in glomerulus was up-regulated and was associated with glomerulus regional immune injury in clinical specimen and anti-Thy1 nephritis." (PMID 40458609, 2025). "Conversely, the increased soluble form of recombinant decorin attenuated the glomerular matrix accumulation in the rat model of anti-Thy1 nephritis 209, 210, and soluble recombinant betaglycan also limited the progression of diabetic nephropathy in db/db mice." (PMID 39990662, 2025). "The anti-Thy1 nephritis model was established as the MsPGN model to determine the regulation of CX3CL1 and CX3CR1 during the development of disease." (PMID 40458609, 2025). "We established the anti-Thy1 nephritis model and injected quetmolimab through the tail vein on day 3, the initiation of proliferative phase." (PMID 40458609, 2025). "BA was administered to anti-Thy1 nephritis rats’ model according to the outlined experimental timeline." (PMID 41345104, 2025). "Results showed that CD74 and MIF were up-regulated in glomerulus of anti-Thy1 nephritis on day 7 and decreased by AZD8797." (PMID 40458609, 2025). "We established anti-Thy1 nephritis and blocked the infiltration of CX3CR1+ monocytes/macrophages into injured glomerulus by injecting AZD8797-CX3CR1 antagonist." (PMID 40458609, 2025). "The anti-Thy1 nephritis model effectively mimics the dual pathological changes of human MsPGN, including renal inflammatory infiltration and abnormal MCs proliferation, making it an ideal animal model for MsPGN research." (PMID 41345104, 2025). "In this study, we established Thy-1 rat nephritis models and administered 1.25(OH)2D3 and rapamycin to the experimental groups to observe changes in PCNA and mTOR expression in rat renal tissues at different time points." (PMID 39636964, 2024). "By days 3, 7, and 14, proteinuria levels were significantly reduced in the NVG and NVRG groups relative to the NG, indicating that 1.25(OH)2D3, both alone and in combination with rapamycin, effectively ameliorated Thy-1-induced nephritis." (PMID 39636964, 2024). "In this study, we established a nephritis rat model induced by Thy-1 injection and evaluated renal pathology to elucidate the roles and mechanisms of 1.25(OH)2D3 in glomerulonephritis." (PMID 39636964, 2024). "In this context, in a rat nephritis model induced by the administration of C5b-9 and the anti-Thy-1 antibody, MCs producing IL-36 were found." (PMID 36233224, 2022). "They found that in anti-Thy1 nephritis mesangial cells express VEGFA and the endothelial cells increased their expression of angiopoietin 2 (Angp2)." (PMID 35155460, 2021). "The rat anti‐Thy‐1 nephritis model was successfully established, according to increased urine albumin/creatinine ratio (UACR) in model group." (PMID 33987885, 2021). "In a rat model of anti-Thy1-induced nephritis, differentiation of invading bone marrow cells into endothelial or mesangial cells was also previously reported, suggesting the regular contribution of bone marrow to glomerular cell turnover." (PMID 35008770, 2021).
nephritis (continued). "Similar to these data, everolimus was also reported to inhibit the proliferation, activation and matrix expansion of mesangial cells in a reversible anti-Thy1-induced nephritis rat model." (PMID 35008770, 2021). "We aimed to investigate the underlying mechanism of endothelial cells (ECs) proliferation in anti‐Thy‐1 nephritis." (PMID 33987885, 2021). "Anti-Thy1 nephritis is characterized by acute mesangiolysis followed by early inflammatory cell infiltration, repopulation of the mesangium by new mesangial cells and accumulation of mesangial matrix." (PMID 35008770, 2021). "In chronic anti-Thy1 nephritis, the formation of focal segmental glomerulosclerosis lesions, the degree of interstitial fibrosis and the increase in proteinuria over 14 weeks were ameliorated by everolimus treatment." (PMID 35008770, 2021). "For example, bone marrow cells have been shown to differentiate into endothelial or mesangial cells in anti-Thy1-induced nephritis in rats." (PMID 35008770, 2021). "Our results indicated that VEGFA expression increased significantly in the mesangial area of anti‐Thy‐1 nephritis." (PMID 33987885, 2021). "Anti-Thy1-induced nephritis is an established model of mesangioproliferative glomerulonephritis and is characterized by initial mesangiolysis followed by repair via endothelial and mesangial cell proliferation and accumulation of mesangial matrix." (PMID 35008770, 2021). "Previous studies have shown that many antiproliferative therapies such as PDGF antagonists, heparin, mycophenolate mofetil and the cell cycle inhibitors provide renal protection in the anti-Thy1-induced nephritis." (PMID 35008770, 2021). "Our study also found that VEGFA expression increased along with ECs proliferation on the 7th day of anti‐Thy‐1 nephritis." (PMID 33987885, 2021). "Anti‐Thy1 nephritis is a classical model of self‐limited mesangial proliferative glomerulonephritis with a proliferative phase and a recovery phase." (PMID 33949114, 2021). "Anti-Thy1 nephritis is an experimental model of immune-mediated glomerular disease, induced by an antibody directed against the Thy1 antigen (CD90) which is constitutively expressed in mesangial cells." (PMID 35008770, 2021). "Crosstalk has been demonstrated between MCs and endothelial cells in mesangial proliferative glomerulonephritis (MPGN) using the Anti-Thy1 nephritis model and co-culture of MC and endothelial cells." (PMID 35155460, 2021). "Induction of anti-Thy-1.1 nephritis led to a significant increase of proliferating cells and antagonism of NK1-R with aprepitant restored interstitial proliferation." (PMID 33070237, 2020). "Commonly used animal models of anti-Thy1 nephritis present with reversible mesangial proliferative glomerulonephritis, facilitating the assessment of the acute phase of glomerular disease." (PMID 32344531, 2020). "MMPs-I BB-1101 has shown to reduce proteinuria in rats with anti-Thy1.1 nephritis, an experimental model of glomerular damage induced by antibody against Thy 1 gene." (PMID 31963569, 2020). "Both glomerular and interstitial ED1-positive macrophages were increased in anti-Thy1.1 nephritis animals compared with control rats." (PMID 33070237, 2020). "In fact, inflammation plays a key role in the development of MPGN, including anti-Thy1 nephritis and IgA nephropathy animal models." (PMID 31551783, 2019). "Per immunostaining results, induction of anti-Thy1.1 nephritis resulted in obvious infiltration of monocytes/macrophages and upregulated levels of α-SMA and PCNA in glomeruli, while MPA and CLT markedly downregulated these markers." (PMID 29026082, 2017). "MiR-34a expression was detected in the kidney tissues of the anti-Thy1 nephritis rat model at various time points (days 3, 5, 7, 10, and 14) by real-time qPCR." (PMID 24638095, 2014).
nephritis (continued). "Compared with day 0, on day 7 (the most obvious pathological change), phospho-PDGFR-β was significantly increased (p < 0.05), indicating that PDGFR-β plays a key regulative role in proliferation development in the anti-Thy-1 nephritis." (PMID 24638095, 2014). "Anti-Thy1 nephritis is a rat model of human mesangial proliferative glomerulonephritis, involving a combination of Thy1 antibody and Thy1 antigen in mesangial cells." (PMID 24638095, 2014). "Our results suggested that miR-34a expression was negatively correlated with the degree of cell proliferation in the anti-Thy1 nephritis model." (PMID 24638095, 2014). "Gas6 is expressed in the mesangial area in animal kidney disease models, such as rat anti-Thy-1 nephritis, anti-GBM nephritis and streptozotocin induced diabetic rat and mouse model." (PMID 23826128, 2013). "To obtain basic evidence concerning the beneficial potential of PPARα ligand against MsPGN, we examined the glomerular protective effects of a PPARα agonist, clofibrate, in a well-established rat model of human MsPGN, anti-Thy1 nephritis." (PMID 22675338, 2012). "The induction of anti-Thy1 nephritis decreased these expressions in each group; however, the PPARα and ACOX expressions of both clofibrate treatment groups remained over the baseline level of the control rats." (PMID 22675338, 2012). "In contrast to these metabolic models, the mechanism of glomerular injury of anti-Thy1 nephritis is due to the direct inflammatory response by complement (C5b-9)-induced activation of the NF-κB signaling pathway." (PMID 22675338, 2012). "In the Fib(−) group, the induction of anti-Thy1 nephritis decreased the mRNA expressions of PPARα and ACOX, a result that was identical to the results of the PPRE binding assay and suggesting the deterioration of glomerular PPARα." (PMID 22675338, 2012). "The developmental process of anti-Thy1 nephritis decreased glomerular PPARα expression and weakened its function, while the pretreatment with an appropriate dose of clofibrate appeared to outweigh this deterioration." (PMID 22675338, 2012). "The time course of NF-κB activation appeared to be consistent with that of the pathological activities of anti-Thy1 nephritis in each group." (PMID 22675338, 2012). "In the Fib(−) group, the induction of anti-Thy1 nephritis obviously decreased the PPRE binding activity of PPARα at days 7 and 14 in a time-dependent manner." (PMID 22675338, 2012). "Beneficial effects of mTOR inhibitors were also reported in anti-thy1 nephritis, in experimental membranous nephropathy, in adriamycin induced nephropathy, in unilateral obstructive uropathy and in the murine model of renal polycystic disease." (PMID 22427849, 2012). "Several previous studies reported that the nephrin protein expression in the glomeruli of anti-Thy1 nephritis was weak and exhibited a discontinuous pattern as determined by immunostaining." (PMID 22675338, 2012). "On the other hand, the glomeruli of rats in the shTSP-1 + Thy-1 nephritis group exhibited less GMC proliferation relative to the shCTR + Thy-1 nephritis group and the Thy-1 nephritis group by electron microscopy." (PMID 23554717, 2011). "Meanwhile, the number of proliferating glomerular cells and the total number of glomerular cells in the shTSP-1 + Thy-1 nephritis group were obviously lower than those in the shCTR + Thy-1 nephritis and Thy-1 nephritis groups." (PMID 23554717, 2011). "In the present study, the plasmids of TSP-1 shRNA (shTSP-1) were constructed and transfected into rat kidneys via renal artery perfusion followed by electroporation, and then anti-Thy-1 antibody was injected into the rats to induce Thy-1 nephritis." (PMID 23554717, 2011). "The rats were divided into following 4 groups: 1) the Thy-1 nephritis group; 2) the shTSP-1 + Thy-1 nephritis group; 3) the shCTR + Thy-1 nephritis group; 4) the NS group." (PMID 23554717, 2011).
nephritis (continued). "The essential role of VEGF-A in promoting glomerular capillary repair has been reported in rat anti-Thy-1 nephritis and in the rat anti-GBM antibody-induced glomerulonephritis model." (PMID 20687922, 2010). "Thus, the use of the anti-Thy1.1 nephritis model provided valuable insights into glomerular repair after IgAN as well as potential therapeutic targets." (PMID 38716725, 2024). "In our study, we found that Angpt2 expression increased on the 7th day of anti‐Thy‐1 nephritis." (PMID 33987885, 2021). "In this study, the rat anti‐Thy‐1 nephritis model and cell co‐culture system were used to explore the specific mechanism of vascular lesions, and we try to alleviate ECs proliferation by blocking the cell‐cell communication so as to provide new ideas for disease treatment." (PMID 33987885, 2021). "Thus, the aim of the present study was to investigate the reno-protective effects of everolimus vs. BMDSCs on the course of anti-Thy1 nephritis." (PMID 35008770, 2021). "However, heminephrectomy can induce irreversible progressive glomerulosclerosis with crescent formation in anti-Thy1 nephritis." (PMID 32344531, 2020). "We obtained encouraging results that CLT significantly attenuated proteinuria, inflammation, glomerular hypercellularity, and ECM deposition in anti-Thy1.1 nephritis, indicating that CLT was a main contributory ingredient involved in TGV formulations in the treatment of MsPGN." (PMID 29026082, 2017). "Currently, no experimental data demonstrate whether Shenhua Tablet is able to inhibit mesangial cell proliferation in rats with anti-Thy1 nephritis." (PMID 26969153, 2016). "In a rat anti-Thy1 mesangioproliferative nephritis, there was an increase in the expression of the ER stress-inducible chaperones GRP78 and oxygen-related protein 150 in isolated glomeruli, especially in the glomerular epithelial cells and mesangial cells, after the induction of the disease." (PMID 26040555, 2015). "In addition to our in vitro findings, we extended our studies to animal experiments and were the first to test the regenerative potential of CKD-MSCs vs. MSCs from healthy donors in vivo using the acute anti Thy1-nephritis model." (PMID 24667162, 2014). "Third, anti-Thy1 nephritis is a very famous rat model resembling human MsPGN; however this nephritis could be produced only in rats." (PMID 22675338, 2012). "Pretreatment with clofibrate for 5 days and the inductive procedure of anti-Thy1 nephritis did not cause any systemic changes to body weight, food consumption, urine volume, blood pressure, or heart rate." (PMID 22675338, 2012). "To investigate whether PPARα activation improves the disease activity of MsPGN, we examined the protective effects of a PPARα agonist, clofibrate, in a well-established model of human MsPGN, anti-Thy1 nephritis, for the first time." (PMID 22675338, 2012). "However, the protective effect of MSCs in improving anti-Thy1-induced glomerulonephritis could be attributed to suppression of the local and systemic release of inflammatory cytokines and growth factors involved in the pathogenesis of anti-Thy1 nephritis." (PMID 35008770, 2021). "Therefore, we suspected that MCs‐derived VEGFA and ECs‐derived Angpt2 might play important roles in ECs proliferation of anti‐Thy‐1 nephritis." (PMID 33987885, 2021). "Previous findings have shown that mesenchymal stem cells (MSCs) improve renal injury in anti-Thy1 nephritis by preventing the increase in serum creatinine, proteinuria and glomerular histopathology, and this could be mainly attributed to the reduction in cytokine-induced inflammation." (PMID 35008770, 2021). "In anti‐Thy‐1 nephritis, promoting Tie2 phosphorylation could alleviate ECs proliferation." (PMID 33987885, 2021).
nephritis (continued). "However, in a previously published study collagen degradation fragments C1M and C3M were measured in three different rat models for nephropathy, namely renal mass reduction (5/6 nephrectomy), progressive glomerulonephritis (chronic anti-Thy1.1 nephritis) and adenine crystal-induced nephropathy." (PMID 28320405, 2017). "Thus, at the early stage of anti-Thy1.1 nephritis, CLT or CLT-AN inhibited monocyte infiltration into the glomeruli via suppression of pro-inflammatory mediators, which may result from the inhibition of NF-κB signaling pathway." (PMID 29026082, 2017). "At the time point W11 (21 days after the last injection of Thy-1 antibody at W7), urinary proteins in 24 h in experimental groups were still significantly higher than that in the Sham group, indicating that the animal model of chronic anti-Thy-1 nephritis was reliably established." (PMID 26969153, 2016). "Biochemical measurements revealed that AZD8797 attenuated proteinuria of anti-Thy1 nephritis on day 7 with no influence on serum creatinine and blood urea nitrogen (BUN) level." (PMID 40458609, 2025). "Although everolimus was shown to disrupt the repair process in the anti-Thy1 nephritis model, another study demonstrated that it did not disturb the long-term repair process in a rat model of renal thrombotic microangiopathy." (PMID 35008770, 2021). "Previous studies have shown the controversial effects of Gas6/AXL in several kidney disease models, e.g., anti-Thy-1-induced nephritis, anti-glomerular basement membrane (GBM)-induced nephritis, streptozotocin-induced diabetic nephropathy, and renal ischemia-reperfusion." (PMID 32324796, 2020). "Regardless of this limitation, so far anti-Thy-1 nephritis model is the most representative animal model used to search for drug targets against mesangial cell proliferation." (PMID 26969153, 2016). "TTCC inhibition experiments in rat and human MC also did not delineate the specific role of TTCC isoforms, though we have previously shown that although Cav3.2 is upregulated in the cortex of kidneys with Thy1 nephritis, this is not in the glomerular compartment." (PMID 35710406, 2022). "However, previous studies also indicate that mesenchymal stromal cells failed to replace injured cells in anti-Thy1 nephritis but improved anti-Thy1 nephritis via preventing cytokine-driven inflammation." (PMID 35008770, 2021). "Interestingly, the findings in our present study were not completely consistent with that in Daniel's study, as it was shown that the transfer of oligonucleotide against TSP-1 could inhibit glomerular ECM accumulation, but had no significant influence on GMC proliferation of Thy-1 nephritis rats." (PMID 23554717, 2011).